PCSK2 (proprotein convertase subtilisin/kexin type 2)
Description:
Serine endopeptidase which is involved in the processing of hormone and other protein precursors at sites comprised of pairs of basic amino acid residues. Responsible for the release of glucagon from proglucagon in pancreatic A cells. Mediates the release of insulin from proinsulin.
Synonyms: NEC 2; PC2; NEC2; SPC2; NEC-2
Tractability: Small molecule: a high-quality ligand is known. Antibody: UniProt places it where antibodies can reach, with high confidence; UniProt predicts a signal peptide or a membrane-spanning region; its Gene Ontology location is reachable by antibodies, with medium confidence. PROTAC: its protein half-life has been measured; a small molecule that binds it is known.
Target class: Enzyme; Serine protease S8B subfamily; Serine protease SB clan; Protease; Serine protease
Gene: Protein-coding gene on chromosome 20 (17,226,107 to 17,484,578, forward strand). Ensembl gene ENSG00000125851.
Subcellular location: Cytoplasmic vesicle, secretory vesicle; Secreted
Subcellular location (Human Protein Atlas): Vesicles; Predicted to be secreted
Pathways (Reactome):
Metabolism of proteins: Insulin processing
Gene Ontology:
Molecular function: protein binding; serine-type endopeptidase activity; endopeptidase activity; serine-type peptidase activity
Biological process: insulin processing; peptide hormone processing; proteolysis; enkephalin processing; islet amyloid polypeptide processing; nervous system development; protein autoprocessing; protein processing
Cellular component: extracellular region; membrane; neuron projection; secretory granule; transport vesicle
Genetic constraint (gnomAD): Loss-of-function variants: 6 observed, 47.5 expected, observed/expected ratio (o/e) 0.13, 90% interval 0.068 to 0.25. The upper end of that interval is the gene's LOEUF score, 0.25, which puts it in group 1 of 6, group 1 being the genes least tolerant of losing a copy. Missense variants: 449 observed, 712.03 expected, observed/expected ratio (o/e) 0.63, 90% interval 0.58 to 0.68. Synonymous variants: 258 observed, 279.89 expected, observed/expected ratio (o/e) 0.92, 90% interval 0.83 to 1.02.
Homologues: Orthologues: chimpanzee PCSK2 (99% identical), macaque PCSK2 (99% identical), pig PCSK2 (99% identical), dog PCSK2 (98% identical), rabbit PCSK2 (97% identical), mouse Pcsk2 (97% identical), rat Pcsk2 (96% identical), guinea pig PCSK2 (93% identical), tropical clawed frog pcsk2 (88% identical), zebrafish pcsk2 (82% identical), Drosophila melanogaster amon (60% identical), Caenorhabditis elegans egl-3 (58% identical). Paralogues in human: FURIN (45% identical), PCSK6 (44% identical), PCSK1 (44% identical), PCSK5 (43% identical), PCSK4 (41% identical), PCSK7 (35% identical), MBTPS1 (18% identical), PCSK9 (15% identical), TPP2 (14% identical).
Diseases named in the same sentence as PCSK2 in open-access papers:
PCSK2 is named in the same sentence as 37 diseases in open-access papers, as found by Europe PMC text mining. Sharing a sentence is not in itself a finding about the gene and the disease. The quoted sentences say what the papers report.
Obesity (9 papers, 2008 to 2025). Accumulation of substantial excess body fat. "Genetic analyses showed that variants in the genomic regions of PCSK1 and PCSK2 associate with CVD traits, confirming previous reports about the involvement of these genes in obesity and diabetes, glucose homeostasis and insulin secretion." (PMID 36188622, 2022). "More importantly, we have demonstrated that an increase in Scg5 expression is correlated with decreases in body weight and obesity in two congenic mouse models and overexpression results in an in vivo increase in 7B2 protein levels and PCSK2 enzymatic activity." (PMID 18439298, 2008).
diabetes (8 papers, 2013 to 2026). "The aim of this study is to investigate the association between genetic variants of PCSK2 and glucose homeostasis parameters and incident diabetes." (PMID 26607656, 2015). "In conclusion, several genetic variants and haplotypes of PCSK2 were associated with various traits of glucose homeostasis and progression to diabetes." (PMID 26607656, 2015). "Our results indicated that PCSK2 gene polymorphisms are associated with pleiotropic effects on various traits of glucose homeostasis and incident diabetes." (PMID 26607656, 2015). "PCSK2 variants have been consistently reported as diabetes susceptibility genes in previous GWASs." (PMID 40141237, 2025). "Furthermore, individuals with some specific SNPs of PCSK2 were also associated with progression to diabetes during a 5-year follow-up." (PMID 26607656, 2015). "Its influence extends to insulin resistance and diabetes, as it interacts with and controls the PCSK2 gene." (PMID 40141237, 2025). "A trend towards association was also detected at two SNPs reported in the only other reported GWAS of DR in Caucasians; rs12267418 near MALRD1 (p = 0.008) in the DME cohort and rs16999051 in the diabetes gene PCSK2 (p = 0.007) in the PDR cohort." (PMID 29739359, 2018). "This revealed high IP activity in the field of PCSKs, with patents ranging from biomarkers of diabetes (PCSK1 and PCSK2), to biomarkers and drug targets in cancer (FURIN and PCSK6), with the highest number of patents expectedly related to PCSK9." (PMID 36188622, 2022).
type 2 diabetes (5 papers, 2012 to 2023). "Rare variation in PCSK2 has been associated with type II diabetes, autism, and intellectual disability (PMID: 17618154, 3008852, and 25363768)." (PMID 37404330, 2023). "This prohormone convertase is less well studied, and mutations in PCSK2 are commonly associated with impaired glucose homeostasis in the context of type 2 diabetes." (PMID 35955861, 2022). "The proprotein convertase subtilisin/kexin-type 2 gene has been well-documented in its link to susceptibility to type 2 diabetes." (PMID 29739359, 2018). "SNPs in PCSK2 have been shown to be associated with type 2 diabetes in several ethnic populations." (PMID 22470424, 2012). "Finally, PCSK2 is an interesting candidate gene given recent work on the potential relationship between ALS and metabolic phenotypes such as hyperlipidemia, BMI and type 2 diabetes." (PMID 22470424, 2012).
colon cancer (3 papers, 2008 to 2025). "In parallel studies for downregulated genes, we were able to identify seven genes with mutations in colon cancer (DPP10, PCSK2, ADAM33, RELN, CAPN13, ADAMTS1 and ADAMTS15), and five genes with mutations in breast carcinomas (MASP3, ABHD12B, TLL1, CPA3 and DPP6)." (PMID 24243807, 2013). "In proteolysis, we identified the subtilisin PCSK2, with 4-6 fold increases in 8 of its core probe-sets in MG-thymoma and increases in colon cancer, and the endopeptidases PHEX and ADAMTS20 (proteolysis), both up-regulated in MG-thymoma but not in colon cancer." (PMID 18545673, 2008).
gastric cancer (2 papers, 2020 to 2022). A primary or metastatic malignant neoplasm involving the stomach. "Some data suggest that EXO-LNC RNA PCSK2-2:1 may play an important role in the progression of gastric cancer and can be used as a potential marker for diagnosis of gastric cancer." (PMID 36035171, 2022). "It has also been shown that the exosomal PCSK2–2:1 level is significantly related to the tumor size, TNM stage, and venous infiltration and may be developed as a prognostic biomarker of gastric cancer." (PMID 32460771, 2020).
esophageal cancer (1 paper, 2024). A primary or metastatic malignant neoplasm involving the esophagus. "In some previous esophageal cancer studies, Ma and Luo reported that when creating a gene signature with differential expression genes, PCSK2 can negatively influence the prognosis of esophageal squamous cell carcinoma patients (OS: p = 0.0044, DFS: p = 0.100)." (PMID 38893126, 2024).
Hypercholesterolemia (1 paper, 2021). An increased concentration of cholesterol in the blood. "Moreover, proprotein convertase subtilisin/kexin type-2 (PCSK9) inhibitors, potent agents against hypercholesterolemia, might enhance the expression of hepatic low-density lipoprotein receptors and accelerate FVIII degradation within the liver, thereby lowering circulating FVIII levels." (PMID 34072487, 2021).
lymph node metastasis (1 paper, 2024). "In the TCGA-KIRP database, among the two patients with PCSK2 gene mutations, both (100%) died and one (50%) experienced recurrence (lymph node metastasis)." (PMID 38893126, 2024).
Lymphatic Metastasis (1 paper, 2025). Transfer of a neoplasm from its primary site to lymph nodes or to distant parts of the body by way of the lymphatic system. "Only 6 genes, namely CHGA, CHGB, PCSK2, PCSK1N, DLGAP1 and DLGAP3 were down-Regulated in the lymphatic metastasis group." (PMID 41431044, 2025).
melanism (1 paper, 2016). "Genetic variation leading to variation in hormone or neurotransmitter levels related to melanism may affect phenotypes by influencing developmental processes in the brain; juvenile owls with greater PCSK2 gene expression displayed reduced amounts of REM sleep, a more ‘precocial’ phenotype." (PMID 26739645, 2016).
thyroid papillary carcinoma (1 paper, 2022). "In addition, PCSK2 can also be used as an indicator to identify follicular variants of thyroid papillary carcinoma." (PMID 36035171, 2022).
thyroid tumor (1 paper, 2011). A benign or malignant neoplasm affecting the thyroid gland. "Expression of PCSK2 was equally low, PLAB was equally high, whereas RAP2A expression was significantly higher (25.9-fold, P = 0.039) in microdissected carcinoma cells that have invaded through the thyroid capsule and entered blood vessels than in thyroid tumor cells growing under the capsule." (PMID 22046576, 2011).
vitiligo (1 paper, 2021). Generalized well circumscribed patches of leukoderma that are generally distributed over symmetric body locations and is due to autoimmune destruction of melanocytes. "Finally, this study also uncovered previously unknown gene expression changes in the skin of patients with vitiligo, including dysregulation of genes involved in lipid metabolism (such as SFPC and PCSK2)." (PMID 33815367, 2021).
tumor (10 papers, 2013 to 2024). "Moreover, serum exosomal lncRNA PCSK2-2:1 is also considered as a potential diagnostic biomarker for GC due to the fact that the downregulation of PCSK2-2:1 can predict the tumor size, tumor stage, and venous invasion." (PMID 36765913, 2023). "The expression of the serum exosomal lncRNA PCSK2-2:1 is significantly downregulated in GC patients compared with that in healthy controls and is associated with tumor size, tumor stage, and venous invasion, suggesting that exosomal RNA PCSK2-2:1 may be a new prospective biomarker for GC diagnosis." (PMID 35602607, 2022). "The results showed that the expression of KLKB1 (P < 0.01), IL13RA2 (P < 0.01), ABCC8 (P < 0.01), and PART1 (P < 0.0001) was significantly up-regulated, while PCSK2 (P < 0.01) was significantly down-regulated in PanNET tissues compared to the non-tumor tissues." (PMID 31607839, 2019). "PCSK2 is a factor related to tumor development and progression." (PMID 26683928, 2015). "In fact, in some samples the expression of three of these genes, encoding the non-protease homologue DPP10, the proprotein convertase PCSK2 and the mannan-binding lectin serine peptidase 3 MASP3, are reduced up to a thousand fold in tumor tissue when compared to normal mucosa." (PMID 24243807, 2013).
infection (6 papers, 2013 to 2025). The state of being infected such as from the introduction of a foreign agent such as serum, vaccine, antigenic substance or organism. "Both Ad-PDA (n = 7) and Ad-PDB (n = 7) treatment induced comparable expression levels of β cell-related genes, including Slc2a2 and Pcsk2, 3 days after infection, but only in the PDA-transfer group were the expressions sustained for longer than 1 week." (PMID 25397325, 2014). "This approach opens up prospects for studying the cellular consequences of infection; however, other strategies retain their interest, since the disturbances in insulin metabolism (Insulin/proinsulin ratio and PCSK2 inhibition) in the present study were demonstrated by ELISA and real-time RT-PCR." (PMID 34067388, 2021). "PCSK2 mRNA expression decreased at 24 h post-infection or after CVB-FL or CVB-TD transfection, but not after Poly (I:C) transfection (p = 0.002)." (PMID 36560784, 2022). "It is not excluded that the effect of the infection on DNA that we observed plays a role in the alteration of the expression of PCSK2 and other genes." (PMID 34067388, 2021).
cancer (5 papers, 2011 to 2025). A tumor composed of atypical neoplastic, often pleomorphic cells that invade other tissues. "However, programmed cell death 1 (Pdcd1), proprotein convertase subtilisin/kexin type 2 (Pcsk2), and LHFPL tetraspan subfamily member 3 (Lhfpl3) are known to be associated with cancer development." (PMID 35565312, 2022). "However, the rest of the genes (LGI1, PCSK2, CTNND2, SLC6A19, DAO, TMEM82 and CPNE7) could be related to CRC and have been previously identified in other types of cancer." (PMID 30940089, 2019).
adenocarcinoma (1 paper, 2018). A common cancer characterized by the presence of malignant glandular cells. "In the LIMMA analysis of any virus-infected (Virus(+)) (n = 8) versus uninfected primary adenocarcinoma specimens (Virus(−)) (n = 2), ACTC1 and PCSK2 were found to be significantly down-regulated in Virus(+)." (PMID 30134863, 2018).
neurological disease (1 paper, 2017).
PCSK2 also shares sentences with these, for which no sentence is quoted: Hyperinsulinemia (2 papers); autism (1); Bardet-Biedl syndrome (1); breast carcinoma (1); colorectal cancer (1); esophageal squamous cell carcinoma (1); hyperlipidemia (1); hyperplasia (1); hypogonadism (1); Insulin resistance (1); Intellectual disability (1); lung carcinoma (1); Mahvash disease (1); melanoma (1); neuroendocrine tumors (1); Noonan syndrome (1); paraganglioma (1); thymoma (1); viral infection (1).